GALNT10 (polypeptide N-acetylgalactosaminyltransferase 10)
Description:
Catalyzes the initial reaction in O-linked oligosaccharide biosynthesis, the transfer of an N-acetyl-D-galactosamine residue to a serine or threonine residue on the protein receptor. Has activity toward Muc5Ac and EA2 peptide substrates.
Synonyms: GalNAc-T10; GALNACT10; PPGALNACT10; PPGANTASE10
Tractability: Small molecule: a structure with a bound ligand is known; it has a high-quality binding pocket. Antibody: UniProt predicts a signal peptide or a membrane-spanning region; the Human Protein Atlas places it where antibodies can reach. PROTAC: ubiquitination databases record sites on it; its protein half-life has been measured; a small molecule that binds it is known.
Target class: Enzyme; Transferase
Gene: Protein-coding gene on chromosome 5 (154,190,514 to 154,420,984, forward strand). Ensembl gene ENSG00000164574.
Subcellular location: Golgi apparatus membrane
Subcellular location (Human Protein Atlas): Plasma membrane; Golgi apparatus; Nucleoplasm
Pathways (Reactome):
Metabolism of proteins: O-linked glycosylation of mucins
Gene Ontology:
Molecular function: polypeptide N-acetylgalactosaminyltransferase activity
Biological process: protein O-linked glycosylation; protein O-linked glycosylation via N-acetyl-galactosamine
Cellular component: Golgi apparatus; Golgi membrane
Genetic constraint (gnomAD): Loss-of-function variants: 25 observed, 51.12 expected, observed/expected ratio (o/e) 0.49, 90% interval 0.35 to 0.68. The upper end of that interval is the gene's LOEUF score, 0.68, which puts it in group 2 of 6, group 1 being the genes least tolerant of losing a copy. Missense variants: 601 observed, 670.51 expected, observed/expected ratio (o/e) 0.9, 90% interval 0.84 to 0.96. Synonymous variants: 255 observed, 255.54 expected, observed/expected ratio (o/e) 1, 90% interval 0.9 to 1.11.
Homologues: Orthologues: macaque GALNT10 (99% identical), dog GALNT10 (97% identical), pig GALNT10 (97% identical), rat Galnt10 (96% identical), mouse Galnt10 (95% identical), chimpanzee GALNT10 (93% identical), rabbit GALNT10 (91% identical), guinea pig GALNT10 (88% identical), tropical clawed frog galnt10 (74% identical), zebrafish GALNT10 (52% identical), Drosophila melanogaster Pgant9 (39% identical), Drosophila melanogaster Pgant5 (38% identical), and 2 more. Paralogues in human: GALNTL6 (71% identical), GALNT1 (40% identical), GALNT13 (40% identical), GALNT5 (38% identical), GALNT4 (36% identical), GALNT12 (36% identical), GALNT7 (35% identical), GALNT16 (35% identical), GALNT6 (35% identical), GALNT14 (34% identical), GALNT2 (33% identical), GALNT11 (33% identical), and 7 more.
Diseases named in the same sentence as GALNT10 in open-access papers:
GALNT10 is named in the same sentence as 24 diseases in open-access papers, as found by Europe PMC text mining. Sharing a sentence is not in itself a finding about the gene and the disease. The quoted sentences say what the papers report.
hepatoma (6 papers, 2017 to 2023). "Subtle alterations in GALNT10 give rise to aberrant O-glycosylation, thus facilitating tumor cell proliferation in hepatocellular carcinoma and gastric cancer." (PMID 38022687, 2023). "Repression of GALNT10 decreases the expression of Mcl-1 and Bcl-2, increasing sorafenib and doxorubicin resistance of hepatoma cells." (PMID 32182776, 2020). "miR-9 could directly interact with GALNT4 to repress its expression, while Hnf4α elevated GALNT10 levels through the downregulation of miR-122 in hepatitis B virus (HBV)-infected hepatoma cells." (PMID 37193819, 2023). "GALNT10 silencing increases sorafenib sensitivity of hepatoma cells." (PMID 28122358, 2017). "Interestingly, hepatoma cells became more sensitive to sorafenib when GALNT10 was silenced." (PMID 28122358, 2017). "Moreover, GALNT10 is up‐regulated via HBV‐mediated inhibition of miR‐122 and functioned as an oncogene in the progression of hepatocellular carcinoma." (PMID 33301605, 2021).
ovarian carcinoma (5 papers, 2014 to 2026). A malignant neoplasm originating from the surface ovarian epithelium. "In this study, we observed markedly elevated glycosylation levels in metastatic ovarian cancer and identified GALNT10 as a key glycosyltransferase that promotes EMT of ovarian cancer cells." (PMID 41637621, 2026). "A deeper database analysis of genes involved in copy number gains revealed three genes whose expression negatively correlates with ovarian cancer patients’ overall survival in all tested datasets: AhRR, GALNT10, and PPP1R3C." (PMID 37511212, 2023). "GALNT10 was found to be highly predictive of the OS of ovarian cancer." (PMID 36983711, 2023). "However, since the role of GALNT10 in ovarian cancer had already been reported, we focused our attention on AhRR and PPP1R3C." (PMID 37511212, 2023). "In addition, two genes related to glycoprotein synthesis, PSG11 and GALNT10, were found highly predictive for the overall survival time of ovarian cancer patients." (PMID 25551281, 2014). "Moreover, we identified the GALNT10 inhibitor Luteolin, which effectively suppresses ovarian cancer metastasis, modulates the immunosuppressive tumor microenvironment through tumor vascular-immune crosstalk, and exhibits synergistic effects with anti-PD1 therapy." (PMID 41637621, 2026). "Collectively, our findings indicate that GALNT10 facilitates ovarian cancer metastasis through the induction of tumor cell EMT and tumor vascular dysfunction, suggesting that GALNT10 inhibitors represent a promising avenue for the development of novel therapeutic strategies in ovarian cancer." (PMID 41637621, 2026).
ovarian serous carcinoma (5 papers, 2021 to 2023). "Altered glycosylation was found to occur in malignancy and GALNT10 is one of the glycosyltransferases whose expression was associated with poor prognosis in high grade ovarian serous cancer." (PMID 36816023, 2023). "A previous research indicated that overexpression of GALNT10 is associated with an immunosuppressive microenvironment to accelerate cancer development and predicts worse clinical results in high grade ovarian serous carcinoma patients." (PMID 34350290, 2021). "Increased GALNT10 expression also promotes tumor growth by creating an immunosuppressive microenvironment and is associated with poor clinical outcomes in those with high-grade ovarian serous carcinoma." (PMID 36983711, 2023). "GALNT10 can be applied as an independent prognostic factor for advanced ovarian serous carcinoma, which can predict poor prognosis and promote tumor progression." (PMID 33301605, 2021).
gastric cancer (4 papers, 2014 to 2025). A primary or metastatic malignant neoplasm involving the stomach. "In gastric cancer, GALNT10 interacts with HOXD13, modulating cell proliferation and migration." (PMID 39744569, 2025). "Additionally, low intra-tumoral GALNT5 expression was detected in advanced stage gastric cancer patients with poor prognosis, and higher GALNT10 expression was found in diffuse type gastric cancers." (PMID 26848976, 2016).
schizophrenia (3 papers, 2021 to 2024). A major psychotic disorder characterized by abnormalities in the perception or expression of reality. "Expression of Galnt10 in the brain in mice might be related to human schizophrenia, and a recent GWAS showed an unambiguous association between schizophrenia and GALNT10 with other glycosyltransferases." (PMID 34576978, 2021).
epilepsy (2 papers, 2019 to 2022). A brain disorder characterized by episodes of abnormally increased neuronal discharge resulting in transient episodes of sensory or motor neurological dysfunction, or psychic dysfunction. "DLG2 belongs to the gene motif “BGNADP”, which is a network associated with ID and epilepsy, including also BTD, GALNT10, NMUR2, AUTS2, and PTPRD." (PMID 35627244, 2022).
Allergy (1 paper, 2015). An allergy is an immune response or reaction to substances that are usually not harmful. "The aim of our study was to investigate the impact of genetic variants of GRIA1 and GALNT10 genes on ASP allergy in a large Hungarian population of 576 ALL patients." (PMID 26457809, 2015). "Additionally, we also involved SNPs in GALNT10 (Polypeptide N-Acetylgalactosaminyltransferase 10) gene, located also at 5q33, which in the original study were also found to be associated with ASP allergy in the discovery cohort, but could not be confirmed in a relatively small validation cohort." (PMID 26457809, 2015).
Autoimmunity (1 paper, 2009). The occurrence of an immune reaction against the organism's own cells or tissues. "Our study supports this body of evidence but also extends the findings to propose new candidates governing autoimmunity that are implicated in glycosylation (Pomgnt1, Galnt11 and Galnt10)." (PMID 19915720, 2009).
breast carcinoma (1 paper, 2025). "Additionally, ginkgetin-mediated inhibition of the miR-122-5p/GALNT10/Smad3 signaling axis significantly attenuated the migratory capacity of breast cancer MDA-MB-231 cells." (PMID 40762894, 2025). "Moreover, ginkgetin treatment upregulated miR-122-5p, leading to specific binding to the GALNT10 3′-untranslated regions, which ultimately reduced Smad3 mRNA and protein levels in MDA-MB-231 breast cancer cells." (PMID 40762894, 2025).
cholangiocarcinoma (1 paper, 2021). A carcinoma that arises from the intrahepatic biliary tree (intrahepatic cholangiocarcinoma) or from the junction, or adjacent to the junction, of the right and left hepatic ducts (hilar cholangiocarcinoma). "The long noncoding RNA DLGAP1‐AS2 facilitates the malignant progression of cholangiocarcinoma via miR‐505 and GALNT10 and may have potential as a novel target for cholangiocarcinoma therapy." (PMID 33301605, 2021).
depression (1 paper, 2021). "In this study, we found three of these predictive PPD genes (TMEM189, GALNT10 and FBXL20) were also associated with PPD onset in the current study and not with depression per se." (PMID 33664235, 2021). "From these, three genes (TMEM189, GALNT10 and FBXL20) were also associated with PPD onset in this study and not with depression per se (enrichment P = 0.08, indicating no significant overlap than expected by chance)." (PMID 33664235, 2021).
pancreatic adenocarcinoma (1 paper, 2024). "High expressions of GALNT5 and GALNT10 are positively correlated with pancreatic cancer survival, while expressions of GALNT8 AND GALNT10 are negatively correlated with survival in PAAD (pancreatic adenocarcinoma)." (PMID 39433745, 2024).
pancreatic cancer (1 paper, 2024). "The survival map of the hazard ratio showed that only the expressions of GALNT5, GALNT8, GALNT10, and GALNT16 displayed significant differences in prognosis with pancreatic cancer." (PMID 39433745, 2024).
tumor (11 papers, 2013 to 2026). "GALNT10 and GALNT18 are members of the GalNAc polypeptide N‐acetyl‐galactosaminyltransferases, which catalyse O‐linked glycosylation of mucin and can promote EGFR O‐glycosylation and subsequent AKT phosphorylation, leading to tumour proliferation." (PMID 38279874, 2024). "GALNT10 encodes for polypeptide N-acetylgalactosaminyltransferase 10, which is associated with the increased regulatory CD4+ T cell infiltration and decreased granzyme B expression in CD8+ T cells in tumor tissues." (PMID 36609529, 2023). "Activated GALNT10 therefore, facilitates HCC tumor growth in HBV-infected cells, but GALNT10 activity appears to be decreased under the influence of Hnf4α and miR-122." (PMID 27322213, 2016). "TXNIP, TUSC2, PPFIBP2, GALNT10 and MAP2K3 demonstrated varying degrees of methylation on their promoter regions in normal mucosa, normal salivary rinses and HNSCC tumor samples respectively." (PMID 23403885, 2013). "In addition, we found that with the evolution of tumor cell status, the expression levels of FLT3LG, GALNT10, IL1B, and IMPDH1 remained stable while ISG20 gradually increased." (PMID 36816023, 2023). "The results showed that the expression levels of FLT3LG, GALNT10, IL1B, IMPDH1 and ISG20 were higher in tumor cells than in normal cells, while the remaining genes could not be identified because of the low expression levels in tumor cells." (PMID 36816023, 2023). "Notably, a biological function experiment revealed that knockdown of GALNT10 and DLGAP1‐AS2 together inhibited the proliferation, migration and invasion of tumor cells." (PMID 33301605, 2021).
cancer (5 papers, 2017 to 2025). A tumor composed of atypical neoplastic, often pleomorphic cells that invade other tissues. "A previous study demonstrated that GALNT10 affects the sensitivity of cancer cells to tyrosine kinase inhibitor (TKI) therapy." (PMID 28122358, 2017). "Additional genes identified included GALNT10, NPIPB4, POGZ, MED13L and UGGT1, most of which had confirmed roles in cancers." (PMID 40507918, 2025). "GALNT10, a member of the GALNT family, has been studied in a variety of cancers." (PMID 33301605, 2021).
GALNT10 also shares sentences with these, for which no sentence is quoted: autism (2 papers); asthma (1); autoimmune disorders (1); bladder cancer (1); brain cancer (1); cervical cancer (1); liver cancer (1); myocardial infarction (1); Obesity (1).